INS (insulin)
Diseases named in the same sentence as INS in open-access papers (continued):
Sharing a sentence is not in itself a finding about the gene and the disease.
Hypoglycemia (continued). "The test is performed using intravenous insulin (0.1–0.15 unit/kg body weight) administration to induce hypoglycemia (plasma glucose <2.2 mmol/L), which results in a cortisol surge from the adrenal glands." (PMID 37238296, 2023). "We have already detected differences in mitochondrial respiration in immune cells of hyperglycemic pigs expressing mutant insulin C94Y (INSC94Y) which makes it interesting to study the effects of prolonged hypoglycemia in GHR-KO pigs on immunometabolism." (PMID 37189345, 2023). "Its definition is arbitrary and owes its importance to the fact that hypoglycaemia of this severity produces brain dysfunction and suppresses insulin secretion." (PMID 37892096, 2023). "Weight gain during insulin and insulin-analogs use is dose-dependent, related to stimulation of food intake, episodes of hypoglycemia, and fluctuating glucose concentrations." (PMID 37049479, 2023). "It has been reported that the use of an insulin pump can reduce nocturnal hypoglycemia, and this is further reduced by SAP with the control algorithms, which can suspend the basal insulin infusion with sensor-detected or sensor-predicted hypoglycemia." (PMID 36769430, 2023). "Current guidelines do not disclose any algorithm, protocol, or specific recommendation to minimize the frequency of hypoglycemia in patients treated with insulin or antidiabetic agents." (PMID 37876724, 2023). "Insulin autoimmune syndrome (IAS), also known as Hirata’s disease, is a rare disease of immune-mediated hypoglycemia, which is characterized by hypoglycemia due to the presence of high levels of insulin autoantibodies (IAA)." (PMID 37519546, 2023). "Despite the exacerbated cardiorespiratory reflex responses, the baroreflex response mediated through chemoreceptor activation was significantly blunted during insulin‐induced hypoglycaemia." (PMID 36459572, 2023). "When working in manual mode, the pump administers insulin according to the basal schedules set and suspends delivery of basal insulin in case of predicted hypoglycemia." (PMID 36983941, 2023). "One study demonstrated that a very small percentage of histaminergic neurons displayed c-Fos expression following insulin-induced hypoglycemia." (PMID 37448468, 2023). "In the data set there were only n=12 of the patients with CSII who had PLGM, but in these individuals we observed a shorter duration of hypoglycemia when compared with the remaining patients using insulin pump (n=132) (35.3±3.1 vs 54.5±2.4 min, p<0.01)." (PMID 37739421, 2023). "Mistimed or imprecise dosing of insulin increases the likelihood of hypoglycemic events and recurrent episodes of hypoglycemia lead to the development of IAH." (PMID 37942482, 2023). "Attention should be paid to controlling glucose levels to prevent (nocturnal) hypoglycemia in insulin-treated patients." (PMID 36674186, 2023). "The hybrid closed-loop system, an automated insulin delivery system, must be the most promising means to achieve appropriate glycemic control with preventing severe hypoglycemia." (PMID 36769430, 2023). "Hypoglycemia is one of the main concerns during antidiabetic treatment, especially insulin treatment." (PMID 38008775, 2023). "The risk of hypoglycemic complications in PTDM patients was found to be comparable to other types of DM, and basal insulin treatment can negatively affect HRQOL by inducing symptomatic albeit mild hypoglycemia." (PMID 37600749, 2023). "Insulin administration carries risks of developing severe hypoglycemia and cardiovascular complications and occurs more often when patients develop insulin tolerance and an increase in doses is required." (PMID 36830792, 2023). "Regarding the mechanism of insulin, similar to sulfonylureas, the clinical effect of insulin on bone mainly results from the higher incidence of hypoglycemia." (PMID 37161384, 2023).
Hypoglycemia (continued). "A large multicentre trial showed that 87% of the patients achieved complete resolution of severe hypoglycaemia at one year, while only 52% were insulin independent." (PMID 37176684, 2023). "Hypoglycemia and insulin accounted for 14.2%, and each of the remaining medicines constituted less than 10%." (PMID 37378298, 2023). "Continuous glucose monitoring and precautions for intensive insulin therapy are necessary following findings that both repeated and acute occurrences of hypoglycemia can lead to atherosclerosis and CVD events." (PMID 36830610, 2023). "C57BL/6 RIP-Tag2 B6 (RT2;B6) mice have a low frequency of liver metastasis and high mortality after 12 weeks due to hypoglycemia from insulin-producing PanNETs." (PMID 37843277, 2023). "This dysregulation can result in frequent exposure to hypoglycemia once treatment with insulin and/or insulin secretagogues is initiated." (PMID 38298268, 2023). "During daytime, however, the rate of symptomatic level 1 hypoglycemia was increased by 28% in the insulin degludec treatment group compared to insulin glargine U100 (p = 0.01)." (PMID 38089060, 2023). "At both hypoglycemia ranges, insulin boluses per kg of body weight used to induce hypoglycemia and plasma insulin and glucagon levels upon reaching hypoglycemia thresholds were comparable between arms." (PMID 37334295, 2023). "Since refractory hypoglycemia persisted 24 h after the insulin overdose, it was decided to proceed with glucagon treatment (15-30 ng/kg/min titrated to the blood glucose level after a loading dose of 50 ng/kg intravenous bolus infusion)." (PMID 38026640, 2023). "Since elevated IGF-II levels are associated with suppressed plasma levels of insulin (C-peptide) and IGF-I, IGF-II-mediated hypoglycemia was suspected." (PMID 37469410, 2023). "A clinical trial conducted in China using basal-bolus insulin also showed a similar hypoglycemia rate of 28.0%." (PMID 38008775, 2023). "The first small clinical trials comparing closed loop insulin delivery with CSII showed an increase in Time in Range and a reduced risk of hypoglycemia in the OCL group." (PMID 36983941, 2023). "Some described needing to set alarms at night to collect information needed to inform frequent adjustments to background insulin doses/basal rates or address worries about hypoglycemia, with resultant detrimental impacts on their sleep and well-being." (PMID 37795883, 2023). "In all our cases, blood sugar levels were difficult to control during the first few months of life, patients were very sensitive to insulin, and hypoglycemia developed frequently." (PMID 37854477, 2023). "Increased secretion of adrenaline from the adrenal medulla during hypoglycaemia development plays a role in early counterregulation by increasing endogenous glucose production and reducing insulin-stimulated glucose uptake." (PMID 37308751, 2023). "IGF2, similar to insulin, can promote hypoglycemia by enhancing glucose uptake by skeletal muscle and inhibiting glucose release from the liver." (PMID 37152930, 2023). "Edmond administered pancreatic islet transplantation to 7 T1DM patients presenting with pronounced hypoglycemia and metabolic instabilities, culminating in all the patients ceasing insulin administration." (PMID 38089622, 2023). "In the Escalada study, insulin naive patients who initiated treatment with Glargine U100 had a slight increase in hypoglycemia, while insulin experienced patients who switched from any basal insulin to Glargine U100 showed less episodes of the outcome." (PMID 37249450, 2023). "Heterozygotes with knockouts of the regulatory subunits p85, β55, and 50α of PI3K have reinforced sensitivity to insulin, leading to the development of hypoglycemia." (PMID 38018594, 2023). "Exposure of insulin-treated streptozotocin-diabetic rats to recurrent hypoglycemia leads to metabolomic alterations in the hippocampus, as well as increased cerebral ischemic damage potentially via enhanced mitochondrial dysfunction." (PMID 37298308, 2023).
Hypoglycemia (continued). "In Asian patients, vildagliptin as monotherapy or in combination with insulin or metformin showed remarkable improvements in HbA1c levels, with reduced risks of developing hypoglycemia." (PMID 38021574, 2023). "If the pump users do not recognize the warning sounds, the LGS system automatically suspends the basal insulin infusion for up to 2 h in response to sensor-detected hypoglycemia, after which the basal insulin infusion is resumed at the programmed rate." (PMID 36769430, 2023). "We optimized these parameters according to the characteristics of each patient, with three specific objectives: i) to prevent episodes of hypoglycemia, ii) to minimize the severity of hyperglycemia, and iii) to minimize the insulin requirement." (PMID 37089422, 2023). "Congenital hyperinsulinism (CHI) is a genetically heterogeneous disease, in which intractable, persistent hypoglycemia is induced by excessive insulin secretion and increased serum insulin concentration." (PMID 36721237, 2023). "For severe hypoglycemia the RRR was 35% for treatment with insulin degludec compared to insulin glargine, translating into an ARR of 0.3 episodes per person-year (p < 0.05)." (PMID 38089060, 2023). "Fasting hypoglycemia was accompanied by inappropriately high plasma insulin levels in the fasted state, which was also observed in Lsd1KI/KIβ mice." (PMID 36821378, 2023). "Further, insulin‐induced hypoglycaemia increased the resting CSN activity, ventilation and augmented NaCN‐mediated ventilatory responses with a corresponding increase in peripheral chemoreceptor activity in anaesthetized beagle dogs." (PMID 36459572, 2023). "In summary, our data demonstrate that when compared with consumption of a normal breakfast and lunch, fasting for approximately 22 hours decreased hepatic glycogen content and lowered glucagon and EGP during insulin-induced hypoglycemia." (PMID 37166980, 2023). "Predictive LGS (PLGS) algorithms analyze dynamic trends in glucose levels and shut off insulin delivery when hypoglycemia is imminent but before hypoglycemic thresholds are achieved." (PMID 37794113, 2023). "Congenital hyperinsulinism of infancy (CHI) is a rare, inherited condition that is characterized by persistent hypoglycemia and inappropriately elevated insulin secretion." (PMID 37392854, 2023). "Instead, the endogenous secretion of insulin and glucagon was inhibited with somatostatin immediately prior to hypoglycemia and both hormones were matched between groups using intraportal infusions." (PMID 37166980, 2023). "All other critical samples in hypoglycaemia in both individuals revealed appropriate suppression of plasma insulin levels ≤ 0.9 mU/L during hypoglycaemia, with ketones and free fatty acids suppressed." (PMID 37974153, 2023). "The HAT study was an observational study developed to explore the hypoglycemia incidence and awareness among insulin treated patients in Brazil." (PMID 38001509, 2023). "Defensive eating, where patients have to adjust their diet by eating more to prevent hypoglycaemia, indicates too large respective insulin doses." (PMID 37132569, 2023). "While both insulin and glucagon-like peptide-1 receptor agonists (GLP-1 RAs) have proven effective in glycemic control for T2DM, insulin use carries the risk of hypoglycemia." (PMID 37779743, 2023). "Insulin therapy requires effective doctor-patient communication and careful monitoring for hypoglycemia." (PMID 37242426, 2023). "Other possible contributors include a component of increased insulin sensitivity and/or placental insufficiency in late pregnancy contributing to hypoglycemia in some women, or increased inaccuracy of the Libre 1 system throughout pregnancy." (PMID 37902969, 2023). "Recent studies showed that fasting situations guarantee low insulin secretion to avoid hypoglycemia through the cleavage of insulin granules." (PMID 37189396, 2023).
Hypoglycemia (continued). "On the other hand, stimulating dendritic cells in the brain, where Hypoglycemia is present, will indicate insulin release." (PMID 36937314, 2023). "All counterregulatory hormones (glucagon, adrenaline [epinephrine], noradrenaline [norepinephrine], cortisol and growth hormone) increased during hypoglycaemia induction with both insulin products at both doses." (PMID 37308751, 2023). "Special attention should be given to the timing of insulin administration to avoid hypoglycemia during physical activity." (PMID 37836433, 2023). "The Bic gene is found in both mice and humans and has been shown to positively relate to hypoglycemia and improved sensitivity to insulin and glucose uptake." (PMID 37108651, 2023). "This diagnosis was made based on severe recurrent postprandial hypoglycemia, accompanied by elevated endogenous insulin production, and a pancreas that appeared grossly normal on imaging." (PMID 38021505, 2023). "The next stage up was predictive low glucose suspend (PLGS) systems, which include an algorithm that predicts future hypoglycaemia and pre-emptively reduces insulin delivery." (PMID 37289734, 2023). "Clinicians highlighted that much of their confidence was due to these pumps often resulting in less hypoglycemia, a potentially dangerous side effect of poor insulin management, leading to a perception of safer care for patients." (PMID 36989019, 2023). "Hypoglycemic episodes are higher in T1D individuals, for whom insulin therapy is mandatory, and 30–40% of T1D subjects experience an average of 1–3 episodes of severe hypoglycemia each year." (PMID 38003671, 2023). "It has been reported that the combination of insulin and metformin is superior to other combinations in terms of glycemic control, weight gain, and the frequency of hypoglycemia and that metformin is an effective adjunct to insulin in patients with T2DM." (PMID 38234946, 2023). "NaCN‐mediated CSN activity and V ̇E were significantly (P < 0.0001) augmented during insulin‐induced hypoglycaemia." (PMID 36459572, 2023). "Despite a combination of insulin and empagliflozin therapy in the treatment group, we observed similar hypoglycemia occurrence (6%) in the two study groups." (PMID 37194077, 2023). "Switching from other types of basal insulin (detemir and glargine) to insulin degludec showed a high level of glycemic control and significant lowering of overall and nocturnal hypoglycemia in type 1 and type 2 DM in a one-year observational study." (PMID 36601214, 2023). "Upon referral, hypoglycemia was also noted (2.3 mmol/L) while blood insulin level was within the normal range (18.0 mIU/L)." (PMID 38260191, 2023). "The current study aimed to assess the knowledge about hypoglycemia and its management among insulin-requiring DM patients." (PMID 37859676, 2023). "Another educational program for treating diabetic patients with hypoglycemia problems (HyPOS), focused on optimizing intensive insulin therapy." (PMID 37942482, 2023). "Some studies suggest that the lower %CV value of < 33% provides additional protection against hypoglycaemia in patients receiving insulin, which was reached by 66% of our patients." (PMID 36882852, 2023). "Hypoglycaemia was reported by 105 (24.9%) participants; in 77/379 (18.3%) on oral hypoglycaemic drugs only and 28/42 (6.6%) on insulin-based regimes." (PMID 37384066, 2023). "Transdermal drug delivery can enhance insulin delivery efficacy, reduce the likelihood of hypoglycemia, and improve patient compliance and satisfaction." (PMID 37397493, 2023). "Hypoglycemia occurs when a significant basal rate of insulin is delivered due to a human error in insulin pump programming or a device malfunction." (PMID 37629520, 2023).
Hypoglycemia (continued). "In addition, some patients mainly present with fasting or early morning hypoglycemia, which is caused by the separation of insulin and insulin antibodies due to changes in the internal environment during the night (which may be related to decreased insulin antibody affinity)." (PMID 36844104, 2023). "The daily insulin dose is often reduced at the time of initiating sodium-glucose cotransporter-2 (SGLT2) therapy in insulin-treated patients to avoid hypoglycemia." (PMID 38186506, 2023). "The cardiovascular reflex response mediated through CBC stimulation was significantly (P < 0.0001) exacerbated during insulin‐induced hypoglycaemia." (PMID 36459572, 2023). "For instance, nNOS-derived NO production in the VMH is stimulated by insulin-induced hypoglycemia, is required for glucose sensing by VMH glucose-inhibited neurons, and is necessary for the usual counter-regulatory response to hypoglycemia." (PMID 37962950, 2023). "Generally, insulin output between meals is balanced by counteracting hormones such as glucagon and adrenaline to prevent overcompensation and hypoglycaemia." (PMID 36999224, 2023). "Accordingly, if aerobic exercise is planned and happens 2–3 h after a meal, reducing the meal’s insulin bolus is a good strategy to avoid hypoglycemia." (PMID 36964201, 2023). "In comparison to premixed insulin, basal insulin has lower rates of hypoglycemia and higher dosing flexibility." (PMID 36624650, 2023). "Other factors, such as time constraints, inappropriate timing for insulin administration, the inherent complexity of insulin regimens, and fear of pain and hypoglycemia were observed as reasons to miss the insulin doses." (PMID 37240580, 2023). "The general hypoglycemia and the stimulated insulin secretion when β-SKO mice or freshly isolated islets were challenged with amino acids indicate that the phenotype of the β-SKO model is similar to that of global knockouts Still, there are some differences." (PMID 37392854, 2023). "Mild hypoglycemia was observed along time analysis in the group administered with 6 U/kg of insulin; severe hypoglycemia was recorded in rats administered with 8 U/kg." (PMID 37110230, 2023). "In an animal model, insulin-induced severe hypoglycemia led to QTc prolongation and multiple types of cardiac arrhythmias with high-degree atrioventricular block, often preceding mortality." (PMID 37887414, 2023). "The top 10 antidiabetic agents with the highest number of hypoglycemia reports were insulin, metformin, exenatide, glimepiride, glipizide, glyburide, sitagliptin, pioglitazone, liraglutide, and dulaglutide." (PMID 37996825, 2023). "Sulfonylurea and insulin prescribers are required to alert their patients to the possibility of hypoglycemia when using these drugs." (PMID 38022365, 2023). "Of all the participants, 302(94.7%) have ever experienced hypoglycemia and only 103 (32.3%) have noticed injection-related complications like rash, swelling, or bleeding after using insulin." (PMID 37143082, 2023). "Variability in glycaemic control improved, and differences between arms in terms of hypoglycaemia, insulin dosing and glucose variability all point towards a favourable metabolic profile and ketone bodies being used as a substrate preferentially over glucose." (PMID 38102152, 2023). "Due to persistence of her hypoglycemia, further testing was done showing high insulin and laboratory parameters consistent with hyperinsulinism." (PMID 37219505, 2023). "Investigates the effects of acute insulin-induced hypoglycemia on inflammation and its potential role in aggravating vascular disease." (PMID 38022365, 2023). "On the other hand, in those patients with level 3 hypoglycemia, metglitinides and insulin use were the greatest while SGLT2i was the least prescribed antidiabetic agent." (PMID 37494344, 2023). "The complex, which combined IgM-IA and insulin, dissociated, then more insulin was released, resulting in a higher incidence of hypoglycemia." (PMID 37143729, 2023).